RNU6-286P (RNA, U6 small nuclear 286, pseudogene)
Gene: Small nuclear RNA gene on chromosome 21 (13,621,577 to 13,621,683, forward strand). Ensembl gene ENSG00000207476.
Homologues: Orthologues: chimpanzee U6 (98% identical), macaque U6 (92% identical), macaque U6 (90% identical), guinea pig U6 (79% identical), dog U6 (76% identical), pig U6 (68% identical). Paralogues in human: U6 (100% identical), RNU6-1021P (99% identical), RNU6-631P (98% identical), RNU6-749P (98% identical), U6 (98% identical), RNU6-127P (93% identical), RNU6-1239P (93% identical), RNU6-1268P (93% identical), RNU6-473P (93% identical), RNU6-617P (93% identical), RNU6-816P (93% identical), RNU6-848P (93% identical), and 1287 more.